HSPB1 (heat shock protein family B (small) member 1)
Diseases named in the same sentence as HSPB1 in open-access papers (continued):
Sharing a sentence is not in itself a finding about the gene and the disease.
amyloid (2 papers, 2022 to 2024). "Among the genes involved in this signaling pathway, p38 MAPK axis-related gene heat shock protein beta-1 (Hspb1) was significantly upregulated over 4.5-fold in response to IT in amyloidosis-induced mice." (PMID 35099007, 2022). "Moreover, when ubiquitously expressed, HSPB1 ameliorated some of the pathological, synaptic, and cognitive symptoms observed in a mouse model of amyloid pathology." (PMID 38507480, 2024). "In conclusion, to our knowledge, this is the first demonstration of one possible mechanism in which exercise additively enhances the expression of HSPB1 in the presence of amyloid deposition, and activates the anti-amyloid activity of HSPB1 (p-HSPB1), which prevents amyloidosis in vivo." (PMID 35099007, 2022). "Notably, levels of both phosphorylated p38 MAPK and total HSPB1 were additively enhanced in amyloidosis-induced IT mice (FI) compared to the VS group." (PMID 35099007, 2022). "Therefore, we consider the induction of p-HSPB1 to be one possible mechanism for IT-mediated prevention of AApoAII amyloidosis." (PMID 35099007, 2022). "Thus, we suggest that the induction of p-HSPB1 could be a novel mechanism by which exercise reduces amyloidosis." (PMID 35099007, 2022). "As HSPB1 is a unique molecular chaperone identified from our transcriptome sequencing, we propose a potential mechanism whereby the upregulation of the p38 MAPK signaling pathway could be a key event for exercise adaptation and the prevention of amyloidosis." (PMID 35099007, 2022). "However, our data showed that IT and amyloidosis induced upregulation of Hspb1 and HSPB1 in the liver and spleen but did not increase other common HSPs, such as Hsp70/Hspa1b and Cryab (also known as Hspb5)." (PMID 35099007, 2022). "Therefore, IT-induced higher expression of Hspb1 in AApoAII amyloidosis might be independent of HSF1 and regulated by other transcription factors." (PMID 35099007, 2022).
astrocytoma (2 papers, 2015 to 2016). "Additionally, two new important targets were uncovered: NOVA1 useful for diagnostic refinement differentiating astrocytoma from oligodendroglioma, and HSPB1/HSP27, as a predictive factor of poor prognosis for GBM." (PMID 26108672, 2015). "They identified RNA binding protein NOVA-1 (NOVA1) to be a marker distinguishing astrocytoma with oligodendrogliomas and heat shock protein beta 1 (HSPB1) as a predictive marker for poor prognosis for GBM15." (PMID 27246909, 2016).
atrial fibrillation (2 papers, 2011 to 2025). A disorder characterized by an electrocardiographic finding of a supraventricular arrhythmia characterized by the replacement of consistent P waves by rapid oscillations or fibrillatory waves that vary in size, shape and timing and are accompanied by an irregular ventricular response. "Compared to patients with paroxysmal atrial fibrillation, those with persistent AF typically exhibit significantly lower HSPB1 expression levels, making them a more responsive target population for HSP inducer therapy." (PMID 40786071, 2025). "We previously demonstrated the small heat shock protein, HSPB1, to prevent tachycardia remodeling in in vitro and in vivo models for Atrial Fibrillation (AF)." (PMID 21731611, 2011). "The research found that serum HSP levels (including HSPB1, HSPA1, HSPB7, and HSPD1) lacked clinical value in predicting postoperative atrial fibrillation (PoAF)." (PMID 40786071, 2025).
autoimmune disease (2 papers, 2018 to 2021). A disorder resulting from loss of function or tissue destruction of an organ or multiple organs, arising from humoral or cellular immune responses of the individual to their own tissue constituents. "However, the roles of HSPB1 in immune modulation and more autoimmune diseases are still unknown and deserve further study." (PMID 34431214, 2021). "Coincidently, vimentin and other proteins specifically upregulated at day 1 pi with E75CV1, such as HSPB1, enolase or LCP-1, share both their potential role in immune defense and their description as autoantigens in autoimmune disorders." (PMID 30208957, 2018).
Charcot-Marie-Tooth disease type 2 (2 papers, 2017 to 2022). A Charcot-Marie-Tooth disease characterized by abnormalities in the axon of the peripheral nerve cell. "Mutations in the small heat shock protein Hsp27, encoded by the HSPB1 gene, have been shown to cause Charcot Marie Tooth Disease type 2 (CMT-2) or distal hereditary motor neuropathy (dHMN)." (PMID 28595321, 2017). "Mutations in HSPB1, HSPB8, and HSPB3 are implicated in inherited peripheral neuropathies (IPNs), such as Charcot-Marie-Tooth disease type 2 (CMT2) and distal hereditary motor neuropathies (dHMN)." (PMID 35328016, 2022).
chronic pancreatitis (2 papers, 2024 to 2025). A chronic inflammatory process causing damage and fibrosis of the pancreatic parenchyma. "We modified a genetically engineered chronic pancreatitis (CP) model by inserting the p.D23A mutation into exon 2 of the trypsinogen 7 precursor and demonstrated that overexpression of Hspb1 blocked the development of CP." (PMID 38481805, 2024). "HSPB1 has been detected in the serum of patients with several types of cancer, chronic pancreatitis, or acute ischemic stroke." (PMID 40855499, 2025). "We further evaluated the expression of Hspb1 in patient samples and found that Hspb1 was obviously upregulated in AP samples compared to normal pancreas samples but was decreased in chronic pancreatitis (CP) samples, which are often the result of SAP." (PMID 38481805, 2024). "To explore the role of Hspb1 in SAP, we used Hspb1 knockout (KO) mice, a genetically engineered chronic pancreatitis strain (T7D23A), Anxa2 KO mice, and acinar cell-specific Prdx1 knockout mice." (PMID 38481805, 2024).
cystic fibrosis (2 papers, 2021). Autosomal recessive disorder caused by pathogenic variants in the CFTR gene (cystic fibrosis transmembrane conductance regulator), which encodes a chloride and bicarbonate channel expressed in epithelial cells, and follow the diagnosis criteria. "In humans, three sHSPs (HSPB1/HSP27, HSPB4 and HSPB5) were shown to affect the CFTR (cystic fibrosis transmembrane conductance regulator) protein, whose mutations are the main cause of cystic fibrosis." (PMID 34360841, 2021).
depression (2 papers, 2021 to 2022). "Trystuła M demonstrated that post-stroke depression is associated with HSPB1 over expression." (PMID 34488523, 2021). "This experiment found that the abnormality of EC pathway in depression patients is highly correlated with the up-regulation of HSPB1." (PMID 34488523, 2021). "Therefore, based on the study of this experiment, it will be of great significance to further study the mechanism of action of HSPB1 and depression." (PMID 34488523, 2021). "Furthermore, we speculate that NFKBIB and HSPB1 play an important role in the relationship between these differential proteins and depression." (PMID 34488523, 2021). "Although there is less research on the relationship between HSPB1 and depression, Heat shock protein 70 (HSP70) in the same family has been shown to be closely related to depression." (PMID 34488523, 2021).
diabetic cardiomyopathy (2 papers, 2024). Diabetic cardiomyopathy is a disorder of the heart muscle in people with diabetes. "At present, there are few in-depth studies on HSPB1 in diabetic cardiomyopathy and no relevant reports." (PMID 39711549, 2024).
distal hereditary motor neuropathy type 2 (2 papers, 2021 to 2024). "Mutations in the HSPB1 gene are associated with a distal hereditary motor neuropathy type 2 (dHMN2) or Charcot‐Marie‐Tooth disease type 2F (CMT2F), usually with autosomal dominant inheritance." (PMID 33973728, 2021). "Distal Hereditary Motor Neuropathy type 2 can be caused by any of four genes: HSPB8, HSPB1, HSPB3, or FBXO38 and affects fewer than one in a million people." (PMID 39480826, 2024).
endometriosis (2 papers, 2017 to 2023). The growth of functional endometrial tissue in anatomic sites outside the uterine body. "Nine proteins were reduced in endometriosis, including Azurocidin 1, an important inflammatory mediator, cysteine-rich secretory protein 3 (CRISP-3) and Heat shock protein beta-1 (HSPB1)." (PMID 28174513, 2017). "Nine proteins were quantitatively reduced in endometriosis, including some proteins related with local innate immunity (CRISP-3 and Pglyrp1) and protection against oxidative stress (HSPB1)." (PMID 28174513, 2017).
fibrosis (2 papers, 2024 to 2025). the formation of excess fibrous connective tissue in an organ or tissue in a reparative or reactive process. "Moreover, this study further elucidates that HSPB1 is related to IBD intestinal fibrosis and also provides a valuable target for treatment." (PMID 39863585, 2025). "Therefore, this study further investigated whether HSPB1 was related to IBD intestinal fibrosis." (PMID 39863585, 2025). "In conclusion, our study demonstrated that SAA3 deficiency in fibroblasts promotes the transition to myofibroblasts through HSPB1/NF-κB/TGF-β1/Smads signaling pathway, exacerbating intestinal fibrosis in IBD." (PMID 39863585, 2025). "Multiple hepatic pathological changes including cirrhosis and fibrosis were observed in the ACLF model, which was found to be alleviated by HSPB1." (PMID 39071496, 2024).
gastric cancer (2 papers, 2012 to 2023). A primary or metastatic malignant neoplasm involving the stomach. "In the present study, HSPB1 presented an elevated protein and mRNA expression in a subset of gastric cancer samples." (PMID 22860099, 2012). "Clinicopathological characteristics, ENO1 and HSPB1 expression in gastric cancer samples." (PMID 22860099, 2012).
Hypertension (2 papers, 2015 to 2024). The presence of chronic increased pressure in the systemic arterial system. "ISIAH-specific activation of Fos gene expression, encoding a transcription factor associated with hypertension, most significantly correlates with Hspb1 expression in the hypothalamus of ISIAH rats." (PMID 39594444, 2024).
infarction (2 papers, 2021 to 2026). A localised pathological necrosis of tissue resulting from obstruction of the blood supply usually by a thrombus, an embolus, or vascular torsion. "In mouse infarction models, cardiomyocyte-targeted HSPB1 overexpression reduced collagen deposition and preserved ventricular function, whereas HSPB1 knockdown exacerbated fibrosis and EndoMT activation." (PMID 41816302, 2026).
ischemic stroke (2 papers, 2015 to 2025). A stroke disorder caused by obstruction of blood flow to the brain, due to thrombotic (local blood clot formation) or embolic (due to a blood clot or other material traveling from another site) event. "Among the upregulated genes, Hspa1b, Ccl2, Cxcl2, Ccl3, Serpina3n, Timp1, H19, Hspb1, Ccl20, and Cxcl1 were found to demonstrate significant upregulation in pathological phase of ischemic stroke." (PMID 25861363, 2015).
leiomyoma (2 papers, 2019 to 2025). A well-circumscribed benign smooth muscle neoplasm characterized by the presence of spindle cells with cigar-shaped nuclei, interlacing fascicles, and a whorled pattern. "The five patients shown in the figure are representative of the total seven patients included in the study, based on both 2-DE and Western blotting phosphorylation trend of HSPB1, HSPA5, and VINC (higher in leiomyoma compared to myometrium)." (PMID 31100862, 2019).
microphthalmia (2 papers, 2020 to 2021). Congenital or developmental anomaly in which the eyeballs are abnormally small. "Here, we show for the first time that HSPB1 knockdown causes microphthalmia and lens defects in a Xenopus model, and these defects can be rescued by mouse HSPB1 ectopic expression." (PMID 32420594, 2020). "Further, Hspb1 knockdown in X. tropicalis led to microphthalmia and/or lens defects, and these phenotypes could be effectively rescued by mouse HSPB1." (PMID 32420594, 2020).
motor neuron degeneration (2 papers, 2019 to 2023). "In fact, mutations in genes coding for several HSPs (e.g., HSPB1, HSPB3, HSPB8 and DNAJB6) are causative not only for myopathies, but also for distal hereditary peripheral neuropathies, which are characterized by motor neuron degeneration." (PMID 40757567, 2023). "This could be due to loss of motor neurons or decreased expression by residual motor neurons, similar to decreased HSPB1 protein expression in SOD1G93A mice, which precedes motor neuron degeneration." (PMID 30346063, 2019).
multiple myeloma (2 papers, 2015 to 2022). "In myeloma cell lines, HSPB1 activation reportedly protects cells from apoptosis by blocking the mitochondrial release of the second mitochondria-derived activator of caspase." (PMID 25962073, 2015). "The HSPB1 gene codifies Heat Shock Protein 27 (Hsp27), a cell survival protein found at elevated levels in many human cancers, including prostate, lung, breast, ovarian, bladder, renal, pancreatic, multiple myeloma, and liver." (PMID 35626021, 2022).
multiple sclerosis (2 papers, 2021 to 2024). A progressive autoimmune disorder affecting the central nervous system resulting in demyelination. "In addition, Hspb1 was upregulated in both iTRAQ and PRM, which has been associated with multiple sclerosis in the spinal cord." (PMID 33504361, 2021).
muscle disorders (2 papers, 2017 to 2018). "Conversely, mutations in small HSPs such as HSPB1, HSPB3, HSPB5, HSPB8 and the co-chaperones DNAJB6 and BAG3 have all been associated with motor neuron and muscular diseases." (PMID 28396624, 2017).
osteoarthritis (2 papers, 2024 to 2025). A noninflammatory degenerative joint disease occurring chiefly in older persons, characterized by degeneration of the articular cartilage, hypertrophy of bone at the margins and changes in the synovial membrane. "These cytoprotective roles are essential in cartilage, where declining HSPB1 levels accelerate chondrocyte apoptosis during osteoarthritis." (PMID 41009407, 2025).
preeclampsia (2 papers, 2018 to 2025). Preeclampsia is a hypertensive disorder of pregnancy that is characterized by new-onset hypertension with proteinuria presenting after 20 weeks of gestation, and depending on mild or severe forms may initially present with severe headache, visual disturbances, and hyperreflexia. "All proteins selected by PLSKO have been reported to be related to preeclampsia, including SERPINE1, HSPB1, CXCL10, DKK1." (PMID 40880285, 2025).
psoriasis (2 papers, 2012 to 2019). An autoimmune condition characterized by red, well-delineated plaques with silvery scales that are usually on the extensor surfaces and scalp. "In contrast, keratinocytes in inflammatory skin diseases such as psoriasis and atopic dermatitis (AD) were found to contain significantly higher levels of HSPB1 than keratinocytes of healthy skin." (PMID 31734893, 2019). "Interesting link between HSPB1 and psoriasis emerged from studies aimed at analyzing the phenotype of cells deficient in the DNAJA3 (TID) protein, one of the members of numerous DNAJ (HSP40) family." (PMID 31734893, 2019). "Another study suggested HSPB1 to be among autoantigens of a streptococcal-induced autoimmune response, being one of the targets of the exaggerated T cell response in psoriasis." (PMID 31734893, 2019). "In addition, it has been proposed that HspB1 is a target of the exaggerated T cell response in psoriasis and an antigenic link between psoriasis and inflammatory bowel disease, uveitis, or arteriosclerosis, which are clinically associated pathologies." (PMID 24278676, 2012).
thyroid cancer (2 papers, 2021 to 2022). "A previous study demonstrated that ZNF677 inhibits proliferation, migration, and invasion of thyroid cancer cells and exerts its tumor suppressor functions by inhibiting the phosphorylation of AKT via transcriptional repression of its two downstream targets, CDKN3 and HSPB1 (or HSP27)." (PMID 34360599, 2021).
type 1 diabetes (2 papers, 2021 to 2024). "Here we showed that HSPB1 concentrations were lower in patients with type 1 diabetes than in non-diabetic healthy controls, and animal experiments showed that upregulation of HSPB1 is associated with neuronal protection." (PMID 39711549, 2024).
acute coronary syndrome (1 paper, 2024). Signs and symptoms related to acute ischemia of the myocardium secondary to coronary artery disease. "Increased plasma levels of HSPB1 have been observed in patients with acute coronary syndrome." (PMID 38429673, 2024).
acute myocardial infarction (1 paper, 2019). Necrosis of the myocardium, as a result of interruption of the blood supply to the area. "HSP27 (HSPB1) showed a distinct and characteristic intracellular translocation from the cytoskeletal fraction into the membrane fraction of platelets during acute myocardial infarction that did not occur in the control group." (PMID 31783528, 2019).
acute-on-chronic liver failure (1 paper, 2024). Acute-on-chronic liver failure (ACLF) is an extreme condition during the natural history of chronic HBV infection, with a relatively high short-term mortality. "The mortality rate of acute-on-chronic liver failure (ACLF) remains significantly elevated; hence, this study aimed to investigate the impact of heat shock protein family B (small) member 1 (HSPB1) on ACLF in vivo and in vitro and the underlying mechanism." (PMID 39071496, 2024).
adenoma (1 paper, 2022). A neoplasm arising from the epithelium. "We confirmed exclusive expression of Hspb1 in murine and human adenomas and revealed that upregulation of HSP25 is Wnt‐driven." (PMID 36321561, 2022).
Allergy (1 paper, 2022). An allergy is an immune response or reaction to substances that are usually not harmful. "This protein group includes proteins involved in cell stress response (HSPB1), mucosal protection and allergy (MUC1), complement activation (CD55) and actin polymerization (CAPG, APRT, TPPP3)." (PMID 35590254, 2022).
asthma (1 paper, 2023). "GSEA analysis showed significant differences between different expression groups of HSPB1 in autophagy, asthma, and glutathione metabolism signaling pathways, and different expression groups of SOCS1 in autophagy and folate biosynthesis signaling pathways, etc.." (PMID 36969832, 2023).
Autoimmunity (1 paper, 2023). The occurrence of an immune reaction against the organism's own cells or tissues. "This promiscuity may allow HSPs, including HSPA1A and HSPB1, flexibility in responding to pathogens and other sterile threats, but also increases the potential for cell and tissue damage or autoimmunity if for any reason the anti‐inflammatory response is inhibited." (PMID 37583307, 2023).
brucellosis (1 paper, 2024). Brucellosis is a bacterial infection that spreads from animals to people via unpasteurized dairy products or by exposure to contaminated animal products or infected animals. "In this study, we observed that HSPB1 was significantly upregulated in patients with chronic Brucellosis compared to those with acute Brucellosis and healthy controls." (PMID 39872944, 2024).
carcinoma in situ (1 paper, 2023). "HSPB1 was highly expressed in patients with metastatic breast cancer, but low in those with carcinoma in situ." (PMID 37268925, 2023).
carotid atherosclerosis (1 paper, 2022). A thickening and loss of elasticity of the walls of carotid arteries that occur with formation of atherosclerotic plaques. "Studies have shown that the level of HSPB1 in atherosclerotic plaques is significantly lower than that in healthy blood vessels; moreover, the plasma levels of HSPB1 are dramatically decreased in patients with carotid atherosclerosis compared with healthy people." (PMID 36474716, 2022).